SFR1 (SWI5 dependent homologous recombination repair protein 1)
Description:
Component of the SWI5-SFR1 complex, a complex required for double-strand break repair via homologous recombination. Acts as a transcriptional modulator for ESR1.
Synonyms: C10orf78; MEI5; MEIR5; bA373N18.1; FLJ41960
Tractability: PROTAC: ubiquitination databases record sites on it; its protein half-life has been measured.
Gene: Protein-coding gene on chromosome 10 (104,122,058 to 104,126,385, forward strand). Ensembl gene ENSG00000156384.
Subcellular location: Nucleus
Subcellular location (Human Protein Atlas): Nucleoli rim; Centrosome; Nucleoplasm
Gene Ontology:
Molecular function: protein binding; transcription coactivator activity
Biological process: cellular response to estrogen stimulus; double-strand break repair via homologous recombination; positive regulation of DNA-templated transcription; meiotic DNA recombinase assembly; reciprocal meiotic recombination
Cellular component: nucleolus; nucleoplasm; nucleus; Swi5-Sfr1 complex; nuclear chromosome
Genetic constraint (gnomAD): Loss-of-function variants: 24 observed, 24.88 expected, observed/expected ratio (o/e) 0.96, 90% interval 0.7 to 1.36. The upper end of that interval is the gene's LOEUF score, 1.36, which puts it in group 5 of 6, group 1 being the genes least tolerant of losing a copy. Missense variants: 255 observed, 257.72 expected, observed/expected ratio (o/e) 0.99, 90% interval 0.89 to 1.1. Synonymous variants: 74 observed, 92.55 expected, observed/expected ratio (o/e) 0.8, 90% interval 0.66 to 0.97.
Homologues: Orthologues: chimpanzee SFR1 (99% identical), macaque SFR1 (94% identical), pig SFR1 (83% identical), rabbit SFR1 (78% identical), dog SFR1 (77% identical), guinea pig SFR1 (74% identical), rat Sfr1 (57% identical), mouse Sfr1 (55% identical), tropical clawed frog sfr1 (40% identical), zebrafish sfr1 (33% identical).
Diseases named in the same sentence as SFR1 in open-access papers:
SFR1 is named in the same sentence as 5 diseases in open-access papers, as found by Europe PMC text mining. Sharing a sentence is not in itself a finding about the gene and the disease. The quoted sentences say what the papers report.
breast carcinoma (1 paper, 2013). "Taken together, we propose that SFR1 is a novel transcriptional modulator for ERα and a potential target in breast cancer therapy." (PMID 23874500, 2013). "SFR1 mRNA was detected in ERα-positive MCF7 breast cancer cells as well as Ishikawa endometrial adenocarcinoma cells." (PMID 23874500, 2013). "The overlapping expression of SFR1 with ERα is consistent with their functional interaction in breast cancer cells." (PMID 23874500, 2013). "SFR1 enhances ER’s ligand-independent and ligand-dependent transcriptional activity and also promotes breast cancer cell proliferation." (PMID 23874500, 2013). "Mouse SFR1 mRNA was detected in the mammary tumor of MMTV-int1 transgenic mice, suggesting possible involvement of SFR1 in mammary tumorigenesis." (PMID 23874500, 2013). "A role for SFR1 in the development of mammary tumors is supported by the finding that the mRNA of SFR1 (GenBank: AAH24403) is expressed in mammary tumors of 5-month-old MMTV-Wnt-1 transgenic mice." (PMID 23874500, 2013). "However, SFR1 siRNA treatment completely abolished the estrogen-dependent growth of MCF7 cells, suggesting that SFR1 proteins are essential for ER-dependent cell proliferation and raising the possibility that SFR1 could be a therapeutic target in breast cancer." (PMID 23874500, 2013). "To test whether SFR1 is involved in transcriptional activation of native ERα target genes, we employed chromatin immunoprecipitation (ChIP) assays to look for ERα-dependent recruitment of SFR1 to the ERα binding sites on pS2 and PR promoters in MCF7 breast cancer cells." (PMID 23874500, 2013).
cancer (1 paper, 2013). A tumor composed of atypical neoplastic, often pleomorphic cells that invade other tissues. "Overall, these results indicated that SFR1 plays roles in anti-apoptosis and cell proliferation in cancer cells." (PMID 23874500, 2013). "Manipulating SFR1 expression by knockdown and overexpression revealed a role for SFR1 in ER-dependent and -independent cancer cell proliferation." (PMID 23874500, 2013). "To address the role of SFR1 in ER-positive breast cancer cells, we examined the expression of SFR1 in several human cancer cell lines." (PMID 23874500, 2013).
SFR1 also shares sentences with these, for which no sentence is quoted: autoimmune disease (1 paper); endometrial adenocarcinoma (1); endometrial cancer (1).